FOXC1 (forkhead box C1)
Diseases named in the same sentence as FOXC1 in open-access papers (continued):
Sharing a sentence is not in itself a finding about the gene and the disease.
glaucoma (continued). "In addition, this is the first study to identify hypermorphic variants of this gene and will contribute to a better understanding of the genetic basis of dominant glaucoma, as well as the function of FOXC1." (PMID 25786029, 2015). "Based on this idea, we observed that none of the glaucoma-associated FOXC1 mutations expressed in the cell cultures showed a complete loss-of-function." (PMID 25786029, 2015). "In addition, some studies have implicated FOXC1 in early-onset glaucoma associated with ASD and other ocular or non-ocular diseases." (PMID 38671671, 2024). "Their mother however, had the same FOXC1 variant, but did not present with glaucoma or CHD, though she could have defects pertaining to anterior segment dysgenesis." (PMID 28979898, 2017). "In addition, the previously-reported patient with lack of iris and heterozgyous FOXC1 mutation also had obvious newborn glaucoma, which is not part of classic aniridia." (PMID 21423868, 2011). "In addition, FOXC1 mutations have been implicated in anterior segment dysgenesis (ASD) such as iridogoniodysgenesis, Axenfeld-Rieger syndrome (ARS) and Peter’s anomaly that progress to glaucoma in 50% to 75% of cases." (PMID 21031026, 2010). "Through literature review, several key glaucoma-related genes were identified, including MYOC, TBK1, COL1A1, COL1A2, FOXC1, LRP2, OPTN, and TEK." (PMID 40808675, 2025). "In secondary childhood glaucoma cases, alterations in CYP1B1 (25%), SOX11 (13%), FOXC1 (13%), GJA8 (13%) and LTBP2 (13%) were detected." (PMID 35011756, 2021). "Interestingly, these glaucoma-related genes like MYOC, TBK1, COL1A1, COL1A2, FOXC1, LRP2, and TEK also showed significant differential expression in RCC tissues." (PMID 40808675, 2025). "The initial FOXC1-related phenotype was identified as Axenfeld–Rieger Syndrome Type III (ARS, OMIM #602482), which involves posterior embryotoxon, iris hypoplasia, irido-corneal adhesions and ~ 50% chance to develop glaucoma." (PMID 36284357, 2022). "Apart from one patient (No. 3) with p.Y81_S82insY in FOXC1 gene who presented with unilateral glaucoma, all others presented with bilateral glaucoma." (PMID 34745210, 2021). "We found that FOXC1 knockdown, through regulation of RAB3GAP1, RAB3GAP2 and SNAP25, leads to decrease in both intracellular and extracellular levels of MYOC, tying these genes into a common pathway of glaucoma pathogenesis." (PMID 28575017, 2017). "However, further validation of the interaction between FOXC1 and MYOC in animal models of glaucoma and ocular cell lines would elucidate weather the interaction is specific to HeLa cells or also occurs in tissues affected during glaucoma pathogenesis." (PMID 28575017, 2017). "This represents the first association analysis of TGFβ2, BMP4, and FOXC1; the lack of association of common polymorphism does not provide evidence in support of the hypothesis that these genes play a significant genetic role in the pathogenesis of glaucoma among white British subjects." (PMID 22736943, 2012). "Unlike glaucoma associated with MYOC mutations, i.e., juvenile primary open-angle glaucoma, which has a normal outflow route at birth, the FOXC1 gene mutations identified in this study caused severe angle abnormalities, resulting in perinatal onset of glaucoma." (PMID 39158757, 2024). "Thus, it is important to screen other glaucoma-associated loci and genes for involvement in congenital glaucoma in cases that are either negative or heterozygous for MYOC, CYP1B1, and FOXC1 mutations to have better insight into the disease pathogenesis." (PMID 23378721, 2013). "Other genes, including FOXC1, CYP1B1, LMX1B and MYOC were not expressed substantially in any neural retina cell classes, consistent with their proposed role predominantly in the anterior segment with mutations leading to high intraocular pressure, a major risk factor for glaucoma." (PMID 32555229, 2020).
Axenfeld-Rieger syndrome (49 papers, 2006 to 2025). Axenfeld-Rieger syndrome (ARS) is a generic term used to designate overlapping genetic disorders, in which the major physical condition is anterior segment dysgenesis of the eye. "Specifically, loss-of-function mutations to FOXC1 in humans are associated with Axenfeld-Rieger Syndrome- a condition characterised by anterior segment dysgenesis of the eye66." (PMID 40683913, 2025). "Of clinical significance, mutations in FOXC1 are predominately associated with Axenfeld-Rieger syndrome, which is characterized by abnormal anterior eye segment dysgenesis and secondary glaucoma in a subset of patients." (PMID 38755144, 2024). "Variants in FOXC1 are associated with Axenfeld-Rieger syndrome/anomaly, Peters anomaly, PCG, and increased susceptibility to POAG." (PMID 38755526, 2024). "Forkhead box C1 (FOXC1) belongs to a family of transcription factor genes, and heterozygous variants have been associated with Axenfeld-Rieger syndrome and ASD." (PMID 35327965, 2022). "FOXC1 mutations can lead to Axenfeld-Rieger syndrome which is characterized by developmental defects of the anterior chamber of the eye, maxillary hypoplasia, hypodontia, microdontia, umbilical abnormalities, and sensorineural deafness." (PMID 35911393, 2022). "Mutations in PITX2 or FOXC1 cause Axenfeld-Rieger syndrome, which is characterized by hypoplasia of the anterior segment and mild dental and craniofacial malformations." (PMID 34777465, 2021). "In line with observations in the mouse, loss of FOXC1 in humans is associated with Axenfeld-Rieger Syndrome (ARS) and pathogenic variants in this gene have been identified in ARS patients (MIM 180500)." (PMID 33498686, 2021). "After confirmation of this FOXC1 variant, clinical data on Axenfeld-Rieger syndrome-associated clinical features were collected and analyzed." (PMID 34809627, 2021). "A novel mutation in the FOXC1 gene was reported in a three-generation family with three Axenfeld-Rieger Syndrome (ARS), a developmental disorder affecting structures in the anterior segment of the eye and heart defect patients." (PMID 33193725, 2020). "In keeping with these developmental properties, mutations that impair the activity of FOXC1 result in the heritable Axenfeld-Rieger Syndrome and other congenital disorders." (PMID 30764547, 2019). "FOXC1 was firstly found to be associated with Axenfeld-Rieger syndrome and harbor mutations in patients which were diagnosed as Rieger anomaly (RA), Iris Hypoplasia (IH) and Axenfeld anomaly (AA)." (PMID 29552326, 2018). "Heterozygous FOXC1 mutation and copy number variation are associated with Axenfeld-Rieger Syndrome (ARS), which is characterized by anterior eye segment defects, glaucoma, and cerebral small vessel disease (OMIM 601090)." (PMID 30564302, 2018). "The FOXC1 gene encodes a transcription factor that is crucial to mesodermal, neural crest, and ocular development, and mutations found in FOXC1 have been found to cause dominantly inherited Axenfeld-Rieger Syndrome (ARS)." (PMID 29487724, 2018). "FOXC1 mutations in humans result in developmental malformations of the cerebellum and eye, Axenfeld-Rieger syndrome, and Dandy-Walker malformation." (PMID 26382291, 2016). "FOXC1 mutations cause Axenfeld Rieger syndrome type 3 (ARS) [MIM: RIEG3 602482], which is characterised by anterior chamber eye malformations and increased risk of glaucoma though CHD occurs in a significant proportion of affected individuals." (PMID 25093829, 2014). "It has been estimated that mutations in PITX2 and FOXC1 are associated with 25%–30% of cases of Axenfeld-Rieger syndrome in the United States, although these numbers vary significantly between patient populations." (PMID 22509100, 2012). "Notably, FOXC1, a gene associated with syndromic ophthalmological disease (Axenfeld-Rieger syndrome, type 3; Mendelian Inheritance in Men, MIM #602482), has recently been linked to autosomal dominant CAKUT." (PMID 38154558, 2024).
Axenfeld-Rieger syndrome (continued). "More than 50 different variants in FOXC1 have been associated with Axenfeld-Rieger syndrome type 3." (PMID 35327965, 2022). "In addition, mutations of FOXC1 can lead to the heritable Axenfeld-Rieger Syndrome and other congenital disorders." (PMID 32987825, 2020). "Since deletions of FOXC1 have been associated with microphthalmia, an investigation into the role of FOXC1 in producing developmental eye anomalies, distinct from those associated with Axenfeld-Rieger syndrome, is important in enabling us to delimit the effect of this gene." (PMID 19626132, 2009). "The highly variable phenotypes found in the assessed family spanned the entire spectrum of FOXC1-associated diseases and ranged from congenital glaucoma to Axenfeld-Rieger Syndrome (ARS)." (PMID 35327965, 2022). "As a member of FOX family proteins, FOXC1 was first found to be associated with the ocular dominant genetic disease Axenfeld-Rieger syndrome (ARS)." (PMID 33522955, 2021). "Axenfeld-Rieger syndrome (ARS) patients commonly feature deletion or mutation of one FOXC1 allele, and 31 distinct point mutations have been identified in FOXC1 in association with ARS to date." (PMID 30764547, 2019). "Among them, Foxc1 and Foxc2 have attracted the most attention in view of their association with Axenfeld-Rieger syndrome (ARS)." (PMID 23533700, 2013). "Heterozygous deletion of FOXC1 in 6p25.3 (cases 28 and 32) can lead to Axenfeld-Rieger syndrome (6p25 deletion syndrome); ocular hypertelorism and flat midface are prevalent in affected postnatal cases." (PMID 32863884, 2020). "Mutations in human PITX2 or the forkhead box transcription factor C1 (FOXC1; 6p25, RefSeq NM 001453.2, MIM# 601090) underlie the autosomal dominant disorder called Axenfeld-Rieger syndrome (ARS; MIM# 602482)." (PMID 29664915, 2018). "FOXC1 is an essential component of mesodermal, neural crest and ocular development and is often studied and discussed in relation to Axenfeld Rieger syndrome (ARS)." (PMID 29487724, 2018). "In addition, the ENU hypomorphic Foxc1 mice, when compared to Foxc1 deficient mice, had greater similarity to patients with Axenfeld-Rieger syndrome (ARS) that is due to Foxc1 mutations." (PMID 23024809, 2012). "There is abundant evidence that deletions affecting the 6p24–25 region bearing FOXC1 result not only in Axenfeld-Rieger syndrome but also in corneal opacities, the majority of which by far are due to iridocorneal rather than keratolenticular adhesions." (PMID 21738392, 2011). "Reduced steady-state levels of protein have been proposed as a disease mechanism in other developmental eye diseases caused by mutations in transcription factor genes such as FOXC1 and PITX2 in Axenfeld-Rieger syndrome." (PMID 20221250, 2010). "Additionally, extra-ocular features related to Axenfeld-Rieger syndrome (such as hearing impairment, cardiac abnormalities, and developmental delay) are frequently present in human PCG patients harbouring FOXC1 variants." (PMID 38755526, 2024). "In this sense, mutations and CNVs in FOXC1 and PITX2, both genes responsible of Axenfeld-Rieger syndrome, could perhaps explain some rare cases of aniridia and aniridia-like phenotypes." (PMID 28231309, 2017). "Indeed, deleterious mutations in FOXC1 and PITX2 can cause Axenfeld-Rieger syndrome, an anterior segment dysgenesis disorder characterized by anomalies in the anterior chamber angle, including defects in the drainage structures of the eye30–32." (PMID 29235454, 2017). "Digenic inheritance of FOXC1 and PITX2 mutations was reported in a severely affected individual in a family with several affected members presenting with variable ocular phenotypes associated with Axenfeld-Rieger syndrome." (PMID 27124303, 2016). "FOXC1 has been intensively studied in Axenfeld Rieger syndrome (ARS) patients." (PMID 25093829, 2014). "We investigated the molecular basis of a severe form of Axenfeld-Rieger Syndrome in one family for which no mutation of PITX2 or FOXC1 was found." (PMID 17134502, 2006).
Axenfeld-Rieger syndrome (continued). "Although FOXC1 mutations were found in human Axenfeld-Rieger syndrome which has no skin barrier disorder, the Axenfeld-Rieger syndrome is resulted from FOXC1 haploinsufficiency, which may not functionally damage enough to cause epidermal symptoms." (PMID 27907090, 2016). "Forkhead box C1 (FOXC1) is a member of the family of forkhead box (FOX) transcription factors, originally identified as being involved in Axenfeld-Rieger syndrome." (PMID 25875420, 2015). "In contrast to non-malignant disorders such as Axenfeld-Rieger syndrome and Dandy-Walker syndrome—which are characterized by reduced normal FOXC1 function—the opposite appears generally true in cancer." (PMID 30764547, 2019).
hepatocellular carcinoma (28 papers, 2014 to 2025). A malignant tumor that arises from hepatocytes. "Especially the recent study from Huang and coworkers underlines the impact of CXCL8 on hepatocellular carcinoma metastasis formation in mice via increased FOXC1 expression." (PMID 26859141, 2016). "The association between FOXC1 and chemokine expression was also demonstrated using hepatocellular carcinoma (HCC) cells." (PMID 37208442, 2023). "In another study in hepatocellular carcinoma, FOXC1 knockdown led to a downregulation of the pro-angiogenic factor VEGFA, consistent with the developmental roles of FOXC1 as a VEGF-responsive mediator of blood vessel formation." (PMID 30764547, 2019). "In studies of other cancers FOXC1 appears to promote EMT through broadly comparable mechanisms to those suggested for hepatocellular carcinoma." (PMID 30764547, 2019). "In recent years, an elevated expression of FOXC1 has been detected in different tumors, such as esophageal cancer, hepatocellular carcinoma and osteosarcoma." (PMID 29357938, 2018). "FOXC1 is also being recognized in a wide range of cancers, including acute myeloid leukemia, hepatocellular carcinoma, renal cell carcinoma, gastric cancer, and non-small cell lung cancer." (PMID 27708239, 2016). "A feedback mechanism may also be relevant in hepatocellular carcinoma cells, where induction of FOXC1 expression by IL-8 seems to further enhance expression of the cognate receptor gene, CXCR1." (PMID 30764547, 2019). "Indeed, knockdown of NEDD9 attenuated the invasion of FOXC1-overexpressing cells in vitro and in vivo, highlighting its role as a downstream mediator of FOXC1-dependent EMT in hepatocellular carcinoma." (PMID 30764547, 2019). "Similarly, FOXC1 was found to be upregulated by HIF-1α in studies of hepatocellular carcinoma cells; FOXC1 consequently upregulates IL-8 and other inflammatory mediators." (PMID 30764547, 2019). "In hepatocellular carcinoma, endometrial cancer, as well as both Hodgkin's and Non-Hodgkin's lymphoma, research support the role of FOXC1 as an oncogene, where upregulated FOXC1 expression is linked to increasingly aggressive disease phenotypes." (PMID 29487724, 2018). "Thus far, FOXC1 appears primarily to be a potential oncogene in not only hepatocellular carcinoma, but in endometrial cancer as well." (PMID 29487724, 2018). "In hepatocellular carcinoma (HCC), FOXC1 facilitates C-C motif chemokine ligand 2 (CCL2) or C-X-C motif chemokine receptor 1 (CXCR1) expression to drive tumor-associated macrophage infiltration and metastasis." (PMID 40416363, 2025). "Indeed, overexpression of FOXC1 in low-expressing hepatocellular carcinoma cells led to downregulation of epithelial genes including E-cadherin and β-catenin in parallel with upregulation of the mesenchymal markers vimentin and fibronectin, consistent with activation of an EMT program." (PMID 30764547, 2019). "Expression of FOXC1 was significantly higher in Hepatocellular carcinoma (HCC) tissues than that in corresponding normal tissues." (PMID 29552326, 2018). "FOXC1 induced CTH promoter DNA hypermethylation through upregulation of DNMT3B to promote proliferation and metastasis in primary hepatocellular carcinoma." (PMID 34904288, 2022). "FOXC1 induces CTH promoter DNA hypermethylation through upregulation of DNMT3B to promote proliferation and metastasis in primary hepatocellular carcinoma." (PMID 34970791, 2022). "A fairly large investigation of patients diagnosed with hepatocellular carcinoma (HCC) demonstrated that FOXC1 expression was a powerful, statistically significant prognostic indicator of worse overall survival as well as recurrence free survival, independent of other clinical variables." (PMID 34540690, 2021). "FOXC1 upregulates the expression levels of CCL2 and CXCR1 by directly binding to their promoters in hepatocellular carcinoma cells." (PMID 33968763, 2021).
hepatocellular carcinoma (continued). "FOXC1 induces EMT through inhibition of E-cadherin expression and promotes cell migration and invasion in hepatocellular carcinoma." (PMID 27409677, 2016). "FOXC1 and FOXC2 were required for intestinal regeneration by stimulating paracrine CXCL12 and Wnt signaling, and FOXP1 downregulation inhibited G1/S phase cell cycle arrest by inducing the proliferation of hepatocellular carcinoma." (PMID 38192721, 2023). "The miRNA miR-582-5p is known to suppress the proliferation of a variety of tumors, including hepatocellular carcinoma, colon cancer, and bladder cancer, and this suppression is thought to be related to the target genes CDK1, AKT3, Rab27a, and FOXC1." (PMID 31146370, 2019). "In a study of esophageal carcinoma cells, FOXC1 directly activated transcription of ZEB2, a transcriptional repressor of E-cadherin that may serve a similar role to SNAIL in hepatocellular carcinoma." (PMID 30764547, 2019). "Because FOXC1 is an EMT-related gene, and the relationship between FOXC1 and VEGF-A has also been proved in hepatocellular cancer, here, we also revealed that the knockdown of FOXC1/FOXCUT gene pair could lead to VEGF-A down-regulation." (PMID 24889262, 2014). "IL-8 activates FoxC1 expression via the PI3K/AKT pathway and via hypoxia-inducible factor 1 alpha, and FoxC1 expression induces CXCR1 and CCL2 transactivation and promotes inflammation in hepatocellular carcinoma (HCC) and the migration and invasion of HCC cells." (PMID 32373221, 2020).